PDPN (podoplanin)
Diseases named in the same sentence as PDPN in open-access papers (continued):
Sharing a sentence is not in itself a finding about the gene and the disease.
tumor (continued). "Furthermore, PDPN-induced platelet aggregation stimulates the release of growth factors, such as TGF-β, thereby promoting tumor cell invasion and metastatic progression." (PMID 40149492, 2025). "Interestingly, in the present study, we observed that PDPN on lymphocytes and CLEC-2 on tumor cells were dramatically increased in CRC, which was possibly related to the progression of CRC." (PMID 40693815, 2025). "However, it should be noted that in each tumour type, including LCTs, a significant correlation was observed between the expression of POSTN and PDPN and the number of positive cells and/or the intensity of the reaction." (PMID 41361308, 2025). "Specifically, we demonstrated that acetate produced by F. rodentium increases CD8+ T-cell immunity and modulates PDPN/CLEC-2/PI3K/AKT/mTOR signaling by downregulating PDPN expression on CD8+ T cells and CLEC-2 expression on tumor cells, resulting in the inhibition of CRC." (PMID 40693815, 2025). "The same tumours were also immunohistochemically positive for both POSTN and PDPN." (PMID 41361308, 2025). "Although the PDPN/CLEC-2 axis suggests a unique immunoregulatory pathway, its role in F. rodentium-mediated CD8+ T-cell reprogramming and anti-tumor immunity is currently unknown." (PMID 40693815, 2025). "Both POSTN and PDPN were absent in normal testes, but immunohistochemically present in most tumours, clearly indicating their role in testicular carcinogenesis." (PMID 41361308, 2025). "Recently, a study demonstrated that leucine rich repeat containing 15 (LRRC15) displayed a more specific expression pattern in myCAFs, and targeted depletion of LRRC15+ myCAFs resulted in a substantial 70% reduction in overall PDPN+ CAFs, significantly attenuating PDAC tumour growth." (PMID 39780187, 2025). "Notably, we identified two transmembrane receptors, PDPN and CLEC2, that are related to the anti-tumor effect of F. rodentium." (PMID 40693815, 2025). "Although our results did not substantiate a positive correlation of podoplanin expression in tumor cells or CAFs with traditional histomorphological parameters, we propose a prognostic potential of podoplanin as a tissue-based biomarker in HPV-associated VC." (PMID 40542163, 2025). "In contrast, one of the non-CasMabs against PDPN, NZ-1, showed high reactivity to PDPN in both tumor and normal cells." (PMID 39594582, 2024). "While PDPN was evenly expressed by all LECs as expected, normal LECs retained high LYVE-1 expression whereas tumor-associated LECs were largely LYVE-1 negative." (PMID 38361951, 2024). "The mouse IgG2a type PMab-117 (PMab-117-mG2a) reacted with the PDPN-positive tumor cells but not with normal kidney podocytes and normal epithelial cells from lung bronchus, mammary gland, and corneal." (PMID 39594582, 2024). "Tumor cells of the two cases showed strong immunoreactivity for AE1/AE3, calretinin, cytokeratin 7 (CK7), podoplanin (D2-40), and weak reactivity for Wilm’s tumor gene-1 (WT1), but were negative to chromogranin A (CgA), cluster of differentiation 34 (CD34), and synaptophysin (Syn)." (PMID 39429478, 2024). "Despite being effective in vitro against murine fibroblasts (NIH3T3) with upregulated PDPN expression, anti-PDPN NIR-PIT did not reduce tumor volume in vivo in our study." (PMID 38275890, 2024). "The co-expression of PDPN and TF by GBM cells cooperatively contributes to tumor microthrombosis." (PMID 39682237, 2024). "Differentially regulated plasma miRNAs (p < 0.05 without correction for multiple testing) between patients with podoplanin positive tumour samples (n = 6) versus patients with tumour samples, which did not express podoplanin (n = 38)." (PMID 38613361, 2024). "In contrast, one of the non-CasMabs against PDPN, NZ-1, showed high reactivity to both tumor and normal epithelial cells." (PMID 39594582, 2024).
tumor (continued). "The anti-PDPN antibodies NZ-1 and NZ-8 induce antibody- and complement-dependent cellular cytotoxicity, resulting in the removal of cancer cells and the suppression of TCIPA, tumor growth, and tumor metastases." (PMID 39451677, 2024). "Tumor-secreted and tissue factor (TF)-positive extracellular vesicles are another major proponent of CAT, while emerging studies have discovered a role for podoplanin (PDPN) in intratumoral thrombosis, hyper-coagulation, and enhanced VTE risk." (PMID 40741180, 2024). "To evaluate the association between increased CX3CL1 expression in cervical LN metastatic areas and tumor lymphangiogenesis in patients with OSCC, we analyzed and counted PDPN+ structures around OSCC cancer nests in primary tumors representing the invasive front of OSCC." (PMID 38775151, 2024). "In addition, other important molecules in the signaling of thrombo-inflammation and cancer are thrombin, tumor-expressed ADP, podoplanin (PDPN), tissue factor (TF), and ADAM-13, among many others." (PMID 39337387, 2024). "MiRNA profiles in relation to intratumoral podoplanin expression (yes—tumour sample showed any kind of podoplanin expression vs. no—tumour sample stained negative for podoplanin) were explored." (PMID 38613361, 2024). "Tumor-secreted and tissue factor-positive extracellular vesicles are another major driver of CAT, while emerging studies have discovered a role for podoplanin (PDPN) in intratumoral thrombosis, hyper-coagulation, and enhanced VTE risk." (PMID 40741180, 2024). "Unlike macrophages in the mammary gland, tumor-associated macrophages expressed CD206 and PDPN with greater variability, producing CD206−, CD206lo, and CD206hi populations, and PDPN−, PDPNlo, and PDPNhi populations, respectively." (PMID 38717149, 2024). "Additionally, in several cancer types, CAFs express podoplanin, which correlates with the number of CD31+ blood vessels within tumors and VEGF-C expression in tumor cells." (PMID 39404428, 2024). "PDPN contributes to not only VTE, but also tumor progression and metastasis." (PMID 40741180, 2024). "These TAMs are characterized by the expression of podoplanin (PDPN), which could interact with normalized tumor blood vessels expressing VEGFR3." (PMID 39726782, 2024). "Striking structural and functional similarities with PDPN indicate that the newfound CA9-CLEC2 interaction may be important for future anti-cancer therapies and could contribute to tumor growth and metastasis." (PMID 39768175, 2024). "Based on these studies, podoplanin and CLEC-2 may be predictors of tumour metastasis and targets for future antimetastatic therapy." (PMID 38561690, 2024). "According to PDPN expression in the tumor stroma, we divided all OSCC patients into negative and positive PDPN expression groups." (PMID 37993428, 2023). "In parallel, the scRNA data from 15 PDAC tissues samples also showed higher infiltration of cells expressing SMC/fibroblast markers (PDPN, COL5A1, COL22A1, TIMP3, SPARC, WT1, GFPT2) in samples with higher proportions/fractions of MUC16-expressing tumor (epithelial) cells (n = 7)." (PMID 36816942, 2023). "GBs also release EVs containing podoplanin (PDPN), resulting in platelet activation and a clotting cascade, which can lead to thrombosis in the tumor and peripheral vasculature, although definitely a health risk to patients it is not clear whether this helps or hurts the tumor itself." (PMID 38074665, 2023). "This indicated that tumor cells had only a low and moderate level of CD142 and PDPN, respectively." (PMID 37511344, 2023). "Importantly, our results further revealed that upregulating MFSD4A-AS1 increased, while silencing MFSD4A-AS1 reduced the density of lymphatic or blood vessel (LBV) in tumor tissues, as demonstrated by the CD31+ and PDPN+ LBV per mm2 in tumor sections." (PMID 36606578, 2023).
tumor (continued). "Mechanistically, circITGB6 promotes tumor metastasis through its direct interaction with IGF2BP3, leading to activation of IGF2BP3 and consequent stabilization of its downstream transcript, PDPN mRNA." (PMID 37898647, 2023). "Another study has found that PDPN+CAFs are abundantly present in the tumor center rather than the infiltrative margins, and they are associated with favorable clinicopathological parameters and prolonged tumor-free survival." (PMID 37143134, 2023). "Taken together, platelets and CAFs are likely to mediate tumor cell activities in tumor stroma jointly through CLEC-2 and PDPN, but the underlying mechanisms have not yet been studied." (PMID 36937386, 2023). "Further, when co-cultured with fibroblasts overexpressing podoplanin, the proliferation rate of tumor cells in the mixed spheroids was increased but not with podoplanin negative fibroblasts." (PMID 37091337, 2023). "Although chLpMab-23-f exhibited ADCC activity and exerted a moderate antitumor effect against CHO/PDPN cells, chLpMab-23-f neither exhibited ADCC activity against PC-10 cells nor CDC activity against PDPN-expressing tumor cells." (PMID 37894446, 2023). "Satoshi Takagi reported that platelets could promote the interaction between aggrus/podoplanin and CLEC-2 to promote tumor growth and metastasis." (PMID 35928880, 2022). "Furthermore, tumor stromal cells are also the primary sources of inflammatory cytokines, including TGF-β, IFN-γ, and TNF-α, which are also known as PDPN inducers." (PMID 35159384, 2022). "In addition, the ACTA2, ASPN, PDGFRB, PDPN, COL12A1, EMILIN1, and CDH11 genes were upregulated in CAFs of several tumor types." (PMID 36263012, 2022). "The neoadjuvant AG regimen resulted in a significant reduction in PDPN+ CAF contents and a decrease in extravasated platelet activation through PDPN+ CAF depletion, thereby preventing aggressive tumor cells from spreading, invading, and developing resistance to drugs." (PMID 36225934, 2022). "Previous studies have emphasised on the role of podoplanin in tumor invasion, but no other studies demonstrated a correlation between podoplanin expression and depth of invasion." (PMID 36247509, 2022). "Lymphatic podoplanin deletion did not affect primary tumor growth, LN weight, or content of red blood cells in LNs, in contrast to previous findings where lymphatic Pdpn deletion right after birth increased LN weight and red blood cells in LNs of adult mice." (PMID 35892863, 2022). "So, patients with clinically negative nodes but has increased podoplanin expression in the tumor cells, should be considered for elective neck dissection to prevent the risk of nodal metastasis." (PMID 36247509, 2022). "In the 4T1-bearing mice from the 100 IU+cal group, increased NFs activation (increased α-smooth muscle actin, podoplanin, and tenascin C (TNC)) with a decreased blood flow in the tumor was observed, whereas the opposite effect was observed in the 5000 IU and 100 IU groups." (PMID 36230508, 2022). "G47Δ targets tumor cells independent of PDPN expression, thus killing tumor cells that evade Lp2-CAR T cells." (PMID 35991754, 2022). "Generally, immuno‐based microfluidic and microarray technologies have utilised tetraspanins (CD9, CD81 and CD63) and tumour‐cell surface associated markers such as EpCAM, CA125, CD19, EGFR, EGFRvIII, podoplanin and PDGFR for on‐chip capture of tumour‐EV sub‐populations." (PMID 36239734, 2022). "We observed strong GPR182 staining in PDPN-positive lymphatic vessels within the tumor, while the expression of GPR182 was weak or negative in lymphatics of the adjacent normal skin." (PMID 35013216, 2022). "The tumor cells are positive for the LEC marker D2-40/Podoplanin and negative for the blood endothelial cell (BEC) marker CD34, which characterizes them as LECs." (PMID 36109802, 2022).
tumor (continued). "Furthermore, in a collagen gel invasion assay, PDPN-positive A431 cells exhibited higher invasion activity in the presence of fibroblasts, suggesting that cancer stem cell functions of PDPN-positive A431 cells might be supported by the fibrogenic tumor microenvironment." (PMID 35159384, 2022). "Podoplanin expression is linked to cell migration, epidermal to mesenchymal transition (EMT), and a distinct tumor cell invasion mechanism without EMT." (PMID 36505148, 2022). "This is in contrast to a recent report wherein PDPN was knocked out successfully but did not affect tumor growth characteristics." (PMID 36059614, 2022). "There was a trend towards increased T stage of the tumor with high podoplanin expression, although not statistically significant." (PMID 36247509, 2022). "Interestingly, squamous cell markers such as SALL4, NANOG, SOX2, BMI1, OCT3/4, HIWI, ABCG2, CD133, podoplanin, and ALDH1 also correlate with ESCC tumor stages, therapeutic resistance, relapse, and patient prognosis." (PMID 36474162, 2022). "In the E0771 tumor model, no change in lung NF activity was observed, but CAFs in mice fed with a vitamin-D-supplemented diet (5000 IU) were activated as podoplanin, TNC, and PDGFRβ increased." (PMID 36230508, 2022). "For instance, the αSMA, PDPN and PDGFRβ+ populations showed a decrease over time in the CAF+ population, with linear fitting of the data indicating similar temporal dynamics of all three markers in both 4T1 and 4T07 tumours." (PMID 34016130, 2021). "Lambrechts and co-workers classified tumor endothelial cells in different clusters based on the marker genes identified; Lymphatic endothelial cells (PDPN+, PROX1+), tumor-derived blood endothelial cells (FLT1+, IGFBP3+, and SPRY1+), malignant, and non-malignant endothelial cells." (PMID 33763348, 2021). "In this scenario, increased CD177+ and CLEC-2+ immune cell infiltration could ameliorate PDPN functions, leading to reduced CAF contractility and possibly altering their activation state, ultimately hampering CAF-mediated enhancement of tumor growth." (PMID 34879110, 2021). "In addition, PDPN signaling sustains CAF proliferation, creating an environment favorable for tumor growth." (PMID 34879110, 2021). "In order to better characterize these two cell populations, an additional FACs panel including a tumor marker (EpCAM), stem cell markers (CD44, CD24, and CD133) and mesenchymal‐like and mesothelial cell markers (CD90, podoplanin and mesothelin) was established." (PMID 34060699, 2021). "Additionally, correlations between Tregs and CTLs infiltration and the expression of tumor PD-L1 and various well-established CSCs markers (i.e. NANOG, SOX2, OCT4, Nestin and PDPN) are also assessed." (PMID 34201050, 2021). "A limited number of spindle tumor cells was positive for GFAP and podoplanin in all cases." (PMID 33576087, 2021). "Given that many cell types can express PDPN in the TME, we next asked whether PDPN expression was derived primarily from fibroblasts or tumor cells." (PMID 34879110, 2021). "Intratumoral application of artLCMV vectors changed the non-hematopoietic tumor stroma with a significantly increased proportion of PDPN+ FSCs, while the fractions of CD31+ blood endothelial cells and PDPN-negative FSCs cells were reduced." (PMID 34354077, 2021). "Anti-PDPN and LAMA4 staining appeared to be primarily cytosolic in tumor cells from this sample." (PMID 32571313, 2020). "By using anti-PDPN CasMab, it is possible to specifically target PDPN expressed on tumor tissues but not on normal tissues." (PMID 33238582, 2020). "Evidence exists that the tumour cells of oral cavity SCC have the capacity to induce the differentiation of CAFs and that these in turn would induce the expression of PDPN in tumour cells through the secretion of TGF-β, favouring EMT and invasiveness of the carcinoma." (PMID 31967978, 2020).
tumor (continued). "Podoplanin (PDPN, tumor cells): CLEC-2 (platelet) and HMGB1 (tumor cells): TLR4 (platelets) are other adhesion protein-ligand pairs that support platelet activation and aggregation on tumor cells, and ultimately metastasis." (PMID 33042789, 2020). "Specifically, the activation of PDPN in tumour cells would stimulate invadopodia formation and degradation of the extracellular matrix, processes that promote epithelial-mesenchymal transition (EMT) and tumour metastasis." (PMID 31967978, 2020). "DDR1 staining is more evident in samples with ALI than those without, whereas PDPN expression is uniquely localized in the invasion front or outward regions of ALI positive tumor sections." (PMID 32244515, 2020). "In most cases, we observed a low degree of PDPN expression (72%), with three samples showing a negative reaction (IRS = 0).The staining was observed at the tumour invasive front, where epithelial tumour cells showed a membrane staining pattern at the basal and suprabasal layers of the epithelium." (PMID 31967978, 2020). "In addition to collagen, we also found that PDPN and LAMA4 were highly overexpressed in HSA tumor tissue when compared to normal tissue." (PMID 32571313, 2020). "In addition, PDPN increases MMP activity in tumour cells and MASL, by targeting PDPN, blocks ECM degradation that is required for malignant cell invasion." (PMID 32326143, 2020). "We have successfully produced anti-podoplanin CasMabs, such as LpMab-2 and LpMab-23 that specifically recognize cancer-type podoplanin in tumor tissues and not in normal-type podoplanin, which is expressed in lymphatic vessels." (PMID 33088928, 2020). "Podoplanin was identified as a marker of CAFs in a variety of malignancies, including cancers in which it is absent from tumor cells, such as adenocarcinomas of breast, lung, or pancreas." (PMID 30736372, 2019). "We also showed that ectopic expression of podoplanin in pre-malignant mouse keratinocytes promoted lymph-node metastasis upon injection into mice; however, whether or not this was associated with enhanced lymphangiogenesis in the primary tumor or in the lymph nodes was not analyzed." (PMID 30736372, 2019). "Thus, interference of the interaction between podoplanin in cancer cells and CLEC-2 in platelets using small-molecule compounds, is a potential therapeutic strategy to block tumor metastasis and invasion." (PMID 31553741, 2019). "Additionally, it was shown that in-vitro PDPN-mediated invasion depends on the activity of matrix metalloproteinases (MMP) degrading ECM surrounding the tumor." (PMID 30654768, 2019). "The interaction between PDPN and CLEC-2 is postulated to regulate tumor invasion and metastasis." (PMID 31321241, 2019). "It has been proposed that tumor-related thrombosis, subsequent inflammation, and inflammation-induced cachexia are related to the CLEC-2-podoplanin interaction and that anti-podoplanin has the potential to prevent tumor metastasis and progression in cancer patients." (PMID 31321241, 2019). "Importantly, the induction of the lymphatic markers PROX-1, VEGFR-3, and podoplanin (PDPN), expressed in KS tumor cells, requires the activation of both JAK/STAT and PI3K/Akt pathways." (PMID 31354653, 2019). "Besides, several specific antibodies generated against cancer-specific highly glycosylated podoplanin were shown to efficiently block the CLEC-2/Podoplanin interaction, subsequent platelet aggregation and tumor metastasis." (PMID 29497419, 2018). "On the other hand, the interaction between podoplanin on tumor cells and CLEC-2 on platelets is hopeful target for suppressing metastasis of podoplanin-positive tumors, because CLEC-2 null platelets show aggregation induced by physiological agonists such as thrombin, ADP, and collagen." (PMID 28674748, 2017).